SMCO2 (single-pass membrane protein with coiled-coil domains 2)
Synonyms: C12orf70; LOC341346
Tractability: Antibody: UniProt predicts a signal peptide or a membrane-spanning region.
Gene: Protein-coding gene on chromosome 12 (27,446,736 to 27,502,185, forward strand). Ensembl gene ENSG00000165935.
Subcellular location: Membrane
Gene Ontology:
Cellular component: membrane
Genetic constraint (gnomAD): Loss-of-function variants: 17 observed, 20.6 expected, observed/expected ratio (o/e) 0.83, 90% interval 0.56 to 1.24. The upper end of that interval is the gene's LOEUF score, 1.24, which puts it in group 5 of 6, group 1 being the genes least tolerant of losing a copy. Missense variants: 302 observed, 287.25 expected, observed/expected ratio (o/e) 1.05, 90% interval 0.96 to 1.16. Synonymous variants: 100 observed, 106.57 expected, observed/expected ratio (o/e) 0.94, 90% interval 0.8 to 1.11.
Homologues: Orthologues: chimpanzee SMCO2 (97% identical), macaque SMCO2 (90% identical), pig SMCO2 (59% identical), dog SMCO2 (58% identical), rat Smco2 (47% identical), mouse Smco2 (46% identical). Paralogues in human: TMCO5A (17% identical), CCDC188 (15% identical).
Diseases named in the same sentence as SMCO2 in open-access papers:
SMCO2 is named in the same sentence as 1 disease in open-access papers, as found by Europe PMC text mining. Sharing a sentence is not in itself a finding about the gene and the disease.
SMCO2 shares sentences with these, for which no sentence is quoted: tumor (1 paper).